CXCL9 (C-X-C motif chemokine ligand 9)
Diseases named in the same sentence as CXCL9 in open-access papers (continued):
Sharing a sentence is not in itself a finding about the gene and the disease.
infection (continued). "In summary, we project a new role for Lcn2 in pulmonary infections where apart from its role in sequestering iron and inhibiting growth of bacteria, infection-induced Lcn2 can also act on mucosal cells to regulate chemokines such as CXCL9 and restrain inflammation at mucosal sites." (PMID 23185529, 2012). "While this difference may impact the defensive role of CXCL9 during infection with fully virulent B. anthracis, the in vitro data presented here demonstrate that chemokine-mediated antimicrobial activity is applicable to both strains of B. anthracis examined." (PMID 21124994, 2010). "In our model, some chemokines reported to be part of the "1st and 2nd waves" of chemokine expression by DC cells, specifically Xcl1, Cxcl9, Cxcl16, Ccl1, Ccl2, Ccl3, Ccl4, Ccl5, Ccl7 and Ccl8 are expressed at increased levels in lung i.n. samples at 3 weeks post-infection." (PMID 20942964, 2010). "The CXCR3 ligands CXCL9, CXCL10, and CXCL11 are potent chemotactic factors for activated T cells, which are highly susceptible to infection in vivo, and these IFN-γ-inducible chemokines are consistently increased in expression in multiple tissues following SIV infection." (PMID 19149556, 2009). "In a study of host responses to oral transmission of SIV, high CXCL9 and CXCL10 levels in lymph nodes after infection were associated with rapid progression of disease, whereas high levels of these chemokines in the oral mucosa were associated with slow progression of disease." (PMID 19149556, 2009). "Most importantly, chemokine genes e.g., Cxcl9, Cxcl10, Cxcl11, Cxcl13, Ccl3, Ccl5 and Ccl12 that exert a chemotactic signal for the immune cell migration to the site of the injury were upregulated at 72 and 96 hr post infection." (PMID 18558011, 2008). "However, blocking of CXCL9 during the infection failed to confirm causality since it did not impact bacterial load of either the high CXCL9 inducer strain L1A or the low CXCL9 inducer strain L2C." (PMID 40162896, 2025). "Given the importance of persistent inflammation and immune activation in the pathogenesis of post-COVID lung damage, we evaluated whether levels of anti-SARS-CoV-2 IgG and the pro-inflammatory chemokines CXCL9 and CXCL10 were associated with pulmonary sequelae at four months post-infection." (PMID 41425601, 2025). "However, Cxcl9 and Cxcl10 could play a more important role during a secondary infection that involves the adaptive immune response." (PMID 38352492, 2024). "Endothelial cells from infected young mice displayed elevated expression of chemokines (Cxcl9, Ccl2) and leukocyte adhesion markers (Icam1) underscoring that inflammation of lung endothelium during infection could facilitate leukocyte adhesion and thromboinflammation." (PMID 38911865, 2024). "However, CXCL9 levels were higher in those with TCMR compared to infection suggesting lower urinary CXCL9 levels may potentially preclude TCMR as a diagnosis." (PMID 37993798, 2023). "Indeed, despite CXCL9, other tested cytokines had a significant higher level at each time point during Clone 13 infection and compared to MRU25010-30 and Mayotte 2008 conditions." (PMID 37306630, 2023). "Therefore, it is conceivable that CD4 T cells are attracted by CXCL9/10 sources, being myeloid cells or SGECs in the vicinity of sites of infection, in order to facilitate the encounter of MCMV antigen-presenting cells and consequently to perform their effector functions, such as IFNγ production." (PMID 34959486, 2021). "Interestingly, administration of CXCL9 in the infection site in mouse brains infected with a recombinant virus in which the UL13 kinase-dead mutation was repaired increased the accumulation of HSV-1-specific CD8+ T cells and inhibited efficient viral propagation and pathogenicity." (PMID 33256093, 2020).
infection (continued). "Unlike Mycopar, the early induction at 2 MPV of IFN-γ, IL-1α, TNF-α, IL-17 and CXCL9 in pgsN and pgsNQ groups may help in controlling early infection with M. paratuberculosis and provide more protection against associated pathological lesions as was clearly shown in liver." (PMID 32957508, 2020). "Interestingly, and as observed after infection of mice with H. pylori, the expression of the chemokines CXCL9 and CXCL10 was strongly reduced in BCG-infected BATF3-deficient compared to WT mice, whereas CXCL11 expression was unaffected by the BCG infection or the mouse genotype." (PMID 31188899, 2019). "Additionally, 46 genes encoding for secreted proteins may serve as markers in blood for the degree of protection (Cxcl9, Gp2, and Pla2g2d), intensity of infection (Retnla, Saa3, Il6, and Il1b), or adaptive recall responses (Ighg, C1qb)." (PMID 28243609, 2017). "Previous studies have reported that Cxcl9 peaks during the early phases of infection in the upper genital tract and may be involved in Th1 responses, our results suggest that within the uterus, Cxcl9-mediated inflammation remains ongoing even after the initial phase of infection." (PMID 26779389, 2015). "Furthermore, while the kinetics of CXCL9 production were similar between WT and IL-10−/− mice on days 4 and 5 post infection, CXCL9 levels produced by IL-10−/− leukocytes were greater 7 days post infection as compared to levels measured in WT leukocyte conditioned media." (PMID 22880122, 2012). "Infection of rhesus (Macaca mulatta) or cynomolgus (Macaca fascicularis) macaques with pathogenic SIV leads to the induction of multiple inflammatory chemokines in lymph nodes and spleen including: CXCL8; CXCL9, CXCL10, and CXCL11; CCL3, CCL4, CCL5; CCL2; CCL19; and CCL20." (PMID 19149556, 2009). "Cytokine profiling revealed an acute Th1-skewed response, with elevations in CXCL9, CXCL10, IL-27, IFNγ, IL-12, and IL-18 during early infection." (PMID 41636514, 2026). "CXCL9 and CXCL10 are significantly increased (~250-fold) in the plasma profiles of PWH compared to pre-infection levels." (PMID 41516395, 2026). "Late infection featured further Th1 reduction, neutrophil accumulation, and NETs activation (H3cit, NE-DNA, MPO), along with reduced CXCL9 but elevated IL-6, IL-21, IL-27, CXCL10, and S100A8 in blood." (PMID 42112327, 2026). "We found that interferon-stimulated genes, crucial for restricting respiratory virus replication early after infection, such as CXCL10, CXCL9, CXCL11, OAS1, OASL, and ISG15, were significantly upregulated in PCLS 72 h post-infection." (PMID 41239423, 2025). "We quantified serum levels of IL-4, IL-6, IL-8/CXCL-8, IL-27, CCL-2, CXCL-9, CXCL-10, and IgG using Luminex and ELISA assays during the acute and subacute phases of infection." (PMID 40711072, 2025). "In neonatal Swiss mice, USUV infection led to an increase in typical neuroinflammatory cytokines, including IL-6, CCL3, CCL4, CCL5, CXCL9, and CXCL10, with CXCL10 being upregulated to the highest level in this model." (PMID 39907280, 2025). "The cerebral migration of CD8+ T cells depend on chemokines CXCL9 and CXCL10 abundantly secreted by cerebrovascular endothelial cells after infection." (PMID 41422632, 2025). "Real-time PCR analysis of mRNA from whole brain tissue revealed elevated expression of proinflammatory mediators ll-6, Il-1β, Ccl2, Cxcl9, and Cxcl10 in both the WT and eNOS+/− mice 3 days post-MA10 infection." (PMID 40573374, 2025). "CXCL9 is an IFN-γ-induced chemokine that facilitates the migration of Th1 cells to sites of inflammation and infection and mediates Th1-mediated immune reactions." (PMID 40519906, 2025). "The chemotactic agents CXCL9 and CXCL10 attract cells to the infection site, which secrete more pro-inflammatory cytokines, such as TNF-α, IL-1β and IFN-γ, amplifying the process and exacerbating the Th1 response." (PMID 40608568, 2025).
infection (continued). "Urinary chemokines, such as CXCL9/10, offer promise for TCMR detection but are limited by confounders like infection." (PMID 40807111, 2025). "The fact that certain cytokines such as CXCL9, IP-10, and CXCL11 remain unchanged in the Delta infection argues against the dampened immune response being solely due to the viral copy number." (PMID 41157615, 2025). "Although most chemokines/cytokines did not change or remained undetectable during stable infection on days 8 and 12, CXCL9, CXCL10, CXCL11, and IFN-λ1 were increasingly induced at both time points post infection." (PMID 39980752, 2025). "One of the key responses initially induced by IFNγ in macrophages is the release of the chemokines CXCL9, CXCL10 and CXCL11, which attract additional T-lymphocytes and other immune cells from the bloodstream to the focus of infection." (PMID 40762872, 2025). "By 16 hours after infection, chemokine expression was increased in both WT CHIKV–infected WT and MARCO–/– mice in comparison with mock-infected mice; however, Ccl2, Cxcl1, and Cxcl9 expression remained significantly higher in the dLN of WT mice." (PMID 38194268, 2024). "After infection, TLR3 expression and p-NF-κB levels increased in cholangiocytes, leading to increased release of CXCL9 and CXCL10." (PMID 38860860, 2024). "Both CXCL9 and CXCL10 control the spread of infection in the CNS through the recruitment of effector cells, such as phagocytes and lymphocytes, to the CNS." (PMID 38879567, 2024). "In particular, the gamma interferon (IFN- γ) inducible chemokines CXCL9, CXCL10, and CXCL11, and their receptor CXCR3, are involved in T cell and macrophage recruitment to the site of infection." (PMID 39301034, 2024). "A protein array used to detect key cytokines in the supernatant of RRV- and Ro1845-infected cholangiocytes revealed CXCL9 and CXCL10 to be the most prevalent cytokines released following RRV infection after normalization to mock-infected supernatant." (PMID 38860860, 2024). "Chemokine-related genes CXCL9 and CXCL10 were significantly up-regulated in the early phase of infection, while CCL4 was significantly up-regulated in the late phase of infection." (PMID 39026675, 2024). "With the understanding that RRV and Ro1845VP4-G446R can induce the murine model of biliary obstruction, we wanted to evaluate CXCL9 and CXCL10 levels in vivo following infection." (PMID 38860860, 2024). "aureus with knockdown of CXCL9, CXCL10, or both of them was collected after 12 h of infection before treatment with neutrophils or macrophages." (PMID 39001897, 2024). "Chemokines (CCL2, CCL3L1, CCL4, CXCL9, CXCL10, CXCL11, and XCL1) were also significantly upregulated after infection." (PMID 38698849, 2024). "CXCL9 and CXCL11 were identified as expressed in the gut tissue of mice 19 days after infection by Trichuris muris." (PMID 38397178, 2024). "Cytokine analysis indicated CCL5 (RANTES), CXCL9 (MIG), CCL4 (MIP-1B), and IFN-y peak between day 1 and 2 post infection dependent on the route of infection." (PMID 39734493, 2024). "Other reports have demonstrated that CXCL9 and CXCL11 chemokines play an important role in the recruitment of T cells to the site of infection during influenza virus infection." (PMID 39066364, 2024). "We found that CCL5, CXCL9, and CXCL5 were the most expressed chemokines and are probably overexpressed during infection." (PMID 39534703, 2024). "Following the apical infection of hBLEC with both RVFV strains, we observed upregulation of three inflammatory cytokines, i.e., CCL5, CXCL9, and CXCL10, in the apical compartment." (PMID 39345143, 2024). "Over expression of chemokines, chemokine (C-X-C motif) ligand 9 [CXCL9], and CXCL10 in serum during active infection counseled that these chemokines accompanied by IFN-γ play a crucial role in the immunopathogenesis of VL." (PMID 37265481, 2023).
infection (continued). "This was evidenced by significant, or close to significant, interactions between diet and infection for the expression of CXCL9, CXCL10, and TNF, indicating that infection-induced changes in gene expression were attenuated by inclusion of dietary Fer-SL." (PMID 38081984, 2023). "During an infection, monocytes/macrophages acquire the M1 phenotype (IL-10-, IL-12+, NOS+, CXCL9+), which are the major effector cells for the first line of host antibacterial defense." (PMID 37600828, 2023). "This can limit clinical translation especially when candidate biomarkers such as CXCL9 and CXCL10 are identified in a wide range of pathologies such as acute rejection, infection, ATN and IFTA." (PMID 37993798, 2023). "Before infection, the latent condition presented the chemokine panel with near-high levels of CXCL11 and mild or moderate levels of CXCL2, CCL4, CCL2, CCL1, and CXCL9." (PMID 37149713, 2023). "There is a clear reduction of these IFN-γ-inducible chemokines (CXCL9 and CXCL10) in the serum upon infection after anti-IFN-γ." (PMID 37205446, 2023). "The transcriptional changes upon infection were dominated by Ifng and its downstream genes (e.g. Stat1, Irf1, Fcgr1, Nos2, Cxcr3) and IFN-dependent CXCR3 binding chemokines (e.g. Cxcl9, Cxcl10)." (PMID 36400767, 2022). "In response to ocular HSV-1 infection, pro-inflammatory cytokines including IL-1, IL-6 and chemokines including CCL2, CCL3, CCL5, CXCL1, CXCL2, CXCL9, and CXCL10 are produced rapidly following infection by resident cells and infiltrating leukocytes." (PMID 36685562, 2022). "The recruitment of the leukocytes to the liver early after infection with Ad5-RGD and Ad5/3 coincided with the increase in the plasma level of CXCL9, a chemokine primarily involved in the CD8+ T cell response." (PMID 35885002, 2022). "We injected IfnbYFP/YFP mice at the time of infection both with anti-CXCR3 (CXCR3-173 clone) and anti-CXCL9 2A6.9.9 mAb, which blocks the CXCL10-binding site and neutralizes soluble CXCL9, respectively." (PMID 36278864, 2022). "Increased cytokines and chemokines such as IL-6, GM-CSF, IL-1a, IL-15, CXCL9 and CXCL10 and complement system components such as C3 were also observed from 6 to 36 months after infection in patients with chronic disease compared to with retrieved controls." (PMID 36189282, 2022). "Proinflammatory cytokines and chemokines analyses in the BAL showed that VACV∆C7L infection resulted in the release of IFN-γ, IL-6, CCL2, CXCL10, and CXCL9 into the BAL." (PMID 35351885, 2022). "(C) Plasma concentration of interferon alpha and gamma and interferon-stimulated chemokines (CXCL9 and CXCL10) during infection." (PMID 33648633, 2021). "Accordingly, we analyzed the expression of the chemokines CXCL9, CXCL10, and CXCL11 in unvaccinated and vaccinated mice of the strains C57BL/6, IL-23p19−/−, and IL-17A−/− after infection with Mtb via quantitative real-time RT-PCR analysis." (PMID 34351501, 2021). "We also showed an inverse correlation between parasite DNA and the expression of CXCL9, IFN-γ, and perforin genes in the hearts of infected animals at day 13 after infection." (PMID 35095849, 2021). "The present work expanded on these observations by demonstrating that infection with a DL isolate induced comparatively higher TNF, CXCL9 and CXCL10 expression than CL in cultured monocytes obtained from both CL and DL patients." (PMID 34568099, 2021). "CXCL9/CXCR3 can chemotaxis and recruit macrophages and T cells to the site of infection during the invasion of HP." (PMID 33763365, 2021). "Although we observed similar heart inflammatory infiltrates at day 13 after infection, IFN-β, IL-12, CXCL9, IFN-γ, and perforin gene expression were lower in the absence of STING." (PMID 35095849, 2021). "IL-12, CXCL9, IFN-γ, and perforin gene expression was significantly lower in the hearts of STING-KO mice 13 days after infection." (PMID 35095849, 2021).
infection (continued). "During CT, CXCL9 and CXCL10, among others, play important roles in recruiting T cells and macrophages into the brain to maintain the latency of infection." (PMID 34262559, 2021). "This is in line with our unpublished results, which demonstrate that ex vivo infection of vaginal explants with HSV-2 results in upregulation of not only IFN-λ but also several other immune factors, including CXCL9, CXCL10, IL-1α and TNF-α." (PMID 35126336, 2021). "Upon znBAZ infection, CXCR3 ligands, CXCL-9, and CXCL-10 levels were significantly enhanced by 14- and 12-fold, respectively." (PMID 34305935, 2021). "Lower magnitudes of gene regulation was noted in this study after infection compared to ferrets infected with the H1N1 virus A/California/07/2009 although immune response genes such as CCL2, CCL8, CXCL9, and CXCR1 increased over the time course." (PMID 34267262, 2021). "The chemokines CXCL9 and CXCL10 are expressed constitutively by airway epithelium and increase during infection." (PMID 32817719, 2020). "In our study, reduced expression of IFNγ, LTα, ICAM-1, CXCL9 and CXCL10 were in line with impaired recruitment of CXCR3+CD8+ T cells to the brains of mice that received BCG before PbA infection." (PMID 33316929, 2020). "Expression of chemokines involved in immune cell recruitment to tissue sites of infection, CCL5, CXCL10, CXCL9, and IL-15, were significantly lower in lung tissues of HTNV-infected Ifnar1-/- animals compared to WT controls." (PMID 32330200, 2020). "We observed a strong inflammatory gene signature in isolated monocytes during subpatent infection, including increased CXCL10, CXCL9 and STAT1 gene expression." (PMID 32566226, 2020). "In order to analyze that, REX3 reporter mice (CXCL10-BFP and CXCL9-RFP) were infected and, on days 4, 9, 12, and 20 after infection, we quantified the number of those cells by flow cytometry." (PMID 32574175, 2020). "DC isolated early after infection of pigs with either of the two CSFV strains showed prominent upregulation of CCL5, CXCL9, CXCL10, CXCL11, and XCL1, as well as of the cytokines TNFSF13B, IL6, IL7, IL12B, IL15, IL27." (PMID 32733474, 2020). "Reportedly, chemokines are specialized in the recruitment of various cells, including neutrophils (IL-8), monocytes (CCL2), Th1 cells (CXCL9, CXCL10), Th2 cells (CCL17, CCL21), and Th17 cells (CCL20), to sites of infection." (PMID 32231137, 2020). "Here we show that also mDCs fail to accumulate in the dLN during ECTVΔ166 infection which, similar to a virulent ECTV infection, results in absent Ifng upregulation and, likely as a consequence, reduced number of CXCL9‐producing iMOs." (PMID 32657004, 2020). "TSVE moderately up-regulated the mRNA level of IL-6, IL-8, TNF-α, IFN-β, CXCL9 and MX1 over the infection time." (PMID 30866776, 2019). "CXCR3 and its ligands, the IFN-γ-inducible C-X-C chemokines CXCL9, CXCL10, and CXCL11, are important for migration of activated CD4+ Th1 cells to inflamed tissues and sites of infection." (PMID 30915078, 2019). "In neuronal cultures, infection with HSV-1 upregulated IFN-alpha, TNF-alpha, CXCL9, and CXCL10, while addition of NO downregulated all tested cytokines and chemokines." (PMID 30886672, 2019). "As they have a common receptor (CXCR3), CXCL9, CXCL10, and CXCL11 have generally been studied together, and studies of combinations of CXCL9, CXCL10, and CXCL11 in infection, injury, and immunoinflammatory responses have been conducted." (PMID 31836011, 2019). "ZIKV infection in primary Tupaia cells induced an upregulation of cytokine mRNA levels over the infection time, including those of IL-6, IL-8, TNF-α, IFN-β, CXCL9, and MX1, where IL-6, IL-8, and TNF-α mRNA levels were significantly elevated 6 h post-infection." (PMID 31842286, 2019). "We observed significantly increased transcript levels of NOS2, CXCL9, and CXCL10 beginning at day 5 post-infection in DCs isolated from H99γ infected mice compared to DCs from H99 infected mice." (PMID 31273203, 2019).